ENSG00000275589
Gene: Miscellaneous RNA gene on chromosome 12 (53,963,629 to 53,963,697, forward strand). Ensembl gene ENSG00000275589.
Gene Ontology:
Biological process: heterochromatin formation